CD44 (CD44 molecule (IN blood group))
Diseases named in the same sentence as CD44 in open-access papers (continued):
Sharing a sentence is not in itself a finding about the gene and the disease.
ovarian carcinoma (continued). "A meta-analysis of the relationship between CD133 expression, prognosis, and clinical and pathological features of ovarian cancer showed that, unlike CD44, high CD133 expression correlates with a worse prognosis in patients." (PMID 34769230, 2021). "However, the CD44+/CD24- phenotype in ovarian cancer cells determines the CSC properties of newly propagated and invasive tumors, and ovarian cancer patients with this phenotype exhibit enhanced recurrence and shorter progression-free survival." (PMID 34064635, 2021). "In addition, multivariate analysis showed that the upregulation of CD44 was an independent predictive and prognostic factor for both OS and DFS of patients with ovarian cancer." (PMID 34944493, 2021). "CD44 increases invasion and migration activity in non-malignant ovarian cancer cells via exosome transfer." (PMID 34064635, 2021). "Although those markers have been described in a broad sense as ovarian CSC markers, TOV-112D ovarian cancer cell line in fact lacked the expression of surface CD44, being thus ruled out this set of experiments." (PMID 34207464, 2021). "On the contrary, if JNK activation failed to be induced, both CD44 expression and the adhesion ability of ovarian cancer would be inhibited." (PMID 32967712, 2020). "Ascites-derived ALDH+CD44+ tumour cell subsets endow stemness, metastatic and metabolic switch properties via PDK4-mediated STAT3/AKT/NF-κB/IL-8 signalling, suggesting PDK4 as a viable therapeutic molecular target for ovarian cancer management." (PMID 32390009, 2020). "More intriguingly, DCA attenuated the effects of cisplatin on ALDH+CD44+ cancer cells, consistent with previous findings that a dual DCA–platinum drug combination could effectively overcome resistance to cisplatin in ovarian cancer." (PMID 32390009, 2020). "Therefore, here, we evaluate all existing evidence indicating functional CD44 and STAT3 cooperation in the context of tumor metastatic progression, therapy resistance and immunosuppression with the focus on ovarian cancer." (PMID 33335857, 2020). "A previous study identified CD24, CD44, CD117, CD133, and ROR1 as ovarian cancer stem cells." (PMID 32035490, 2020). "Further studies need to be done with PEO1, PEO4, and PEO6 cell lines to determine, between CD44 and CD133, which is a surface marker and which one provides stemness, or whether both have mixed properties in ovarian cancer stem cells along disease progression." (PMID 32188032, 2020). "We have previously reported that both paclitaxel and cisplatin, standard chemotherapies used for the treatment of ovarian cancer patients, promotes an increase in the expression of the chemoresistant markers ERCC1 and TUBB3 and the CSC markers CD44, CD133, OCT4A and EpCAM in ovarian cancer cells." (PMID 33023532, 2020). "Furthermore, CD44+/CD24- expression correlates with increased recurrence rate and reduced progression-free survival in ovarian cancer patients." (PMID 35582216, 2020). "The possibility of targeting CD44/STAT3 axis to boost the antitumor efficacies of PARP inhibitors and overcome PARP inhibitor resistance may lead to better treatment for ovarian cancer patients." (PMID 33335857, 2020). "Cantrixil has shown broad cytotoxic activity against chemoresistant ovarian cancer stem cell (CD44+ MyD88+) populations in both 2D and 3D in vitro models, as well as potent cytotoxic activity against non-stem like ovarian cancer cells." (PMID 32532126, 2020). "Once the presence of EpCAM positive CTCs in the blood of patients was confirmed using two methodologies, an expression profile analysis, including a panel of genes related to cell plasticity and ovarian cancer aggressiveness (MUC1, CK19, CXCR4, TIMP1, ALDH1, CD24, CD44, GDF1), was carried out." (PMID 32423054, 2020). "In the context of ovarian carcinoma, there are no reports analyzing CD44 or STAT3 signaling within CAFs themselves." (PMID 33335857, 2020).
ovarian carcinoma (continued). "CD44 has also been considered as a cancer stem cell (CSC) marker in several malignancies of hematopoietic and epithelial origin, and is closely related with tumor progression and drug resistance in several tumors including ovarian cancer." (PMID 30818864, 2019). "Taken together, our present study indicated that CD44 may be pivotal for EMT and closely correlate with the prognosis of ovarian cancer." (PMID 31497537, 2019). "Additionally, the authors found that sphere-forming cells co-express CD44 and CD117 and that those two specific markers can be used to isolate highly tumorigenic ovarian cancer stem cells." (PMID 31261739, 2019). "A previous study revealed that treatment with cisplatin results in the enhanced expression of cancer stem cell markers—including CD44, α2 integrin subunit, CD117, CD133, and EpCAM—and the upregulation of stem cell factors—such as Nanog and Oct4—in residual ovarian cancer cells in in vitro assays." (PMID 31261739, 2019). "In ovarian cancer network, out of seventy leading hubs in the ovarian cancer network, we could able to explore five such KRs which are AKT1, CD44, MCAM, KRAS and EPCAM." (PMID 31752757, 2019). "It was also found that a reduced expression of CD44, Nanog, Oct4, CXCL16 and EGFR after ST6GALNAC1 silencing in OCSCs indicated that CD90+ stem cells infected with miRNA against ST6GALNAC1 had weaker self-renewal capacity in ovarian cancer." (PMID 30996686, 2019). "Following the definition of key regulators, we could able to identify five KRs, namely, AKT1, KRAS, EPCAM, CD44 and MCAM, that are key regulators (organizers) of the ovarian cancer network." (PMID 31752757, 2019). "CD44 was knocked down by small interfering RNA, the expression of Snail, ZEB1, and Caveolin-1 in a stable Snail-expressing ovarian cancer cell line HO8910PM-Snail (HOPM-Snail) and its control cell line HO8910PM-vector (HOPM) was detected by western blotting analysis." (PMID 31497537, 2019). "To determine whether calcitriol is able to inhibit the expression of these stemness genes in ovarian CSCs, we sorted CD44+CD117+ and CD44−CD117− cells from ovarian cancer cell line 2008 using Fluorescence-activated cell sorting (FACS)." (PMID 29581858, 2018). "Calcitriol treatment significantly reduced both CD44+CD117+ and ALDH+ cells in this ovarian cancer cell line, while knockdown of VDR blocked calcitriol-induced decrease of these cells, indicating that the depletion of CSCs by calcitriol treatment is a VDR-dependent event." (PMID 29581858, 2018). "The aim of the present study was to determine the relative expression, cellular location, and prognostic significance of HER-family members, the EGFR mutant (EGFRvIII) c-MET, IGF-1R and the cancer stem cell biomarker CD44 in 60 patients with FIGO stage III and IV ovarian cancer." (PMID 29731973, 2018). "Taken together, these data indicate that DDB2 silencing is able to facilitate the ovarian cancer cell dedifferentiation, characterized by both CD44−CD117− to CD44+CD117+ cell conversions and ALDH− to ALDH+ cell conversions, as well as the non-tumorigenic to tumorigenic cell conversions." (PMID 29752431, 2018). "Several putative ovarian cancer stem cell markers, such as CD24, CD44, CD133, SOX2, SSEA have been proposed, but the definition of their phenotypical features remains highly variable in the various studies, probably due to the consistent phenotypic and functional plasticity of these cells." (PMID 29389895, 2018). "In our study, SP was detected only in ES2 cell line (0.2% of cells; not shown), and did not correspond to the CD133+/CD44+ population in ovarian cancer cell lines." (PMID 30018258, 2018). "In fact, these authors have shown that primary ovarian cancer specimens were composed of low densities of cells displaying cancer stem cell markers such as ALDH1A1, CD44 and CD133; tumors collected immediately after primary therapy were more densely composed of each of these markers." (PMID 29389895, 2018).
ovarian carcinoma (continued). "Other studies have explored the frequency of ovarian cancer stem cells, identified as CD44+ALDH1+, in a large number of primary tumors: according to the level of CD44 expression the patients were subdivided into two subgroups, high expression (>20% CD44+ cells) and low expression (<20% CD44+ cells)." (PMID 29389895, 2018). "These NPs were selectively internalized by ovarian cancer cells overexpressing CD44, but not by cognate cells lacking this HA receptor." (PMID 28212584, 2017). "In line with this study, we observed that glucose-restricted OVCAR3 Gluc-2 and Gluc-3 sublines had increased expression of ovarian cancer stem cell markers, such as CD44 and CD117, as well as decreased expression of CA125 (MUC16), an ovarian cancer marker negatively correlated with stemness." (PMID 28412735, 2017). "CD44, CD47 and c-met may have synergistic effects on the development of OCCC and are prognostic factors for ovarian cancer." (PMID 25658794, 2015). "No previous CD44 studies have been carried out with paired primary, metastatic, and recurrent tumor tissues from each individual ovarian cancer patient." (PMID 25823654, 2015). "CD44 monoclonal antibody treatment has been shown to inhibit ovarian cancer cell motility but not invasion." (PMID 25687880, 2015). "In this study, we found that CD117+CD44+CSC vaccine significantly suppressed the secretion of TGF-β in ovarian cancer tissues, which may be one of anti-ovarian cancer mechanisms by inhibition of ovarian carcinogenesis and regulating CSC properties." (PMID 26497895, 2015). "Based on the results of CD44 immunostaining in our TMA, we further examined the relative expression levels of CD44 in two pairs of well-characterized drug sensitive and resistant ovarian cancer cell lines-SKOV-3/SKOV-3TR and OVCAR8/OVCAR8TR." (PMID 25823654, 2015). "We are not aware of previous reports describing increases of CD44 and TF after platelet exposure in ovarian cancer." (PMID 25886038, 2015). "However, only a few studies have investigated the relationship between CD44, CD47 and c-met and ovarian cancer, particularly OCCC." (PMID 25658794, 2015). "Here we showed that the SKOV3 CD117+CD44+CSC vaccine elicited strongly anti-ovarian cancer immune responses that significantly led to suppressing tumor growth, decreasing CD117+CD44+CSC and aldehyde dehydrogenase 1 (ALDH1) positive cell populations in tumor tissues in the vaccinated nude mice." (PMID 26497895, 2015). "More importantly, stable CD44 knockdown ovarian cancer cell lines and their negative controls have been well established, characterized, and intensively studied in the current work." (PMID 25823654, 2015). "There appears to be a backfeed interaction between inflammatory mediators and CD44 expression as, tumor necrosis factor-alpha (TNF-alpha), a major inflammatory cytokine, abundant in the ovarian cancer microenvironment was found to differentially modulate CD44 expression in ovarian cancer cells." (PMID 25926834, 2015). "The results demonstrated that the CD117+CD44+CSC vaccine not only markedly decreased the CD117+CD44+CSC population, but also reduced ALDH-positive cell population in SKOV3 ovarian cancer tissues from the vaccinated nude mice compared with the mice vaccinated with other control vaccines." (PMID 26497895, 2015). "Strobel and colleagues found that treatment with neutralizing monoclonal antibody (mAb) to CD44 inhibited the number of peritoneal implants by 70% in ovarian cancer xenograft models, but did not reduce growth rates of tumors." (PMID 24567915, 2014). "However, CD44+ and CD133+ subpopulations in ovarian cancer was believed to be heterogeneous and consisted of progenitor cells and differentiated cells as well." (PMID 22642602, 2012). "From initial studies in human ovarian cancer, both side population (SP) and non-SP in one cell line (MOVCAR8) showed high expression of CD44 whereas other human ovarian cancer cell lines do not express CD44." (PMID 22693526, 2012).
ovarian carcinoma (continued). "Furthermore, we demonstrate a correlation between the percentage of CD44+ EOC stem cells and survival in early-stage ovarian cancer." (PMID 21904548, 2011). "We evaluated invasive markers of urokinase plasminogen activator (uPA) and CD44 and multiple drug-resistance (MDR) markers of MDR1 and MRP2 in four epithelial ovarian cancer (EOC) cell lines, primary tumours (n=120) and matched metastatic lesions (n=40) by immunofluoresence labelling." (PMID 19603017, 2009). "CD44 binds the ECM glycosaminoglycan hyaluronan with high affinity and affects cell adhesion, migration and tumour growth in ovarian carcinoma cells." (PMID 15798771, 2005). "Whereas CD44s was found to be higher and CD44v5 to be lower in ovarian cancer patients than healthy control subjects, no statistical difference between the two cohorts was revealed for CD44 isoform v6." (PMID 9413956, 1997). "Gene expression studies in embryo implantation, endometriosis and ovarian cancer metastasis have all found altered expression of LIF, and other genes such as CD44 and miR 99a-5p, supporting our hypothesis that the uterine secretome is important in benign and malignant processes." (PMID 38728307, 2024). "Moreover, the results of online analysis with TIMER2.0 suggested a positive correlation between PEAR1 and CD44 expression levels in numerous cancers, such as blood, brain, colorectal, and ovarian cancer (data not shown)." (PMID 39145451, 2024). "Studies evaluating gene expression in embryo implantation, endometriosis and ovarian cancer have all found altered expression of LIF, and other genetic and epigenetic changes, such as CD44 and miR 99a-5p, supporting our hypothesis that the uterine secretome is important in all these processes." (PMID 38728307, 2024). "Therefore, the results obtained for CD44 expression did not contradict nor clarify the potential prognostic value of this biomarker in ovarian cancer patients." (PMID 36768723, 2023). "In the present study, we developed PEG-MZF-NPs/DDP/CD44-shRNA magnetic nanoliposomes and inaugurated an integrated therapy through the synergistic effect of MFH, gene therapy, and chemotherapy, and a satisfactory therapeutic effect on ovarian cancer in vitro and in vivo is shown." (PMID 35402279, 2022). "Therefore, we suggest that CD44-shRNA/DDP magnetic nanoliposomes have a selectivity to ovarian cancer tissues and cells and may be a potential candidate for ovarian cancer therapy." (PMID 35402279, 2022). "CD44 is a cell surface receptor, an integral membrane glycoprotein that binds several extracellular matrix (ECM) components, including hyaluronan, and which plays a diverse role in ovarian cancer progression, cell proliferation, migration, invasion, and metastasis." (PMID 36077833, 2022). "The numerous observations that both CD44 and STAT3 are critically involved in the VEGF pathway and tumor angiogenesis indicate that dual targeting of both factors could be a promising therapeutic target to improve antiangiogenic treatment in ovarian cancer." (PMID 33335857, 2020). "These alterations were shown to facilitate the adhesion of ovarian cancer cells mainly via (i) exposure of submesothelial ECM, where cancer cells preferably adhere, and via (ii) upregulated expression of ICAM-1/VCAM-1, HA, and FN1, providing integrin- and CD44-mediated ovarian cancer cell adhesion." (PMID 33270665, 2020). "The presence of TAG72 has been confirmed on MUC1 and CD44 (an ovarian cancer stem cell marker and receptor for the ECM molecule hylauronan) as well as CD133 (a marker present in cancer stem-cells including ovarian cancer) and MUC16 proteins in ovarian cancer patients." (PMID 32937961, 2020). "The high metastatic ovarian cancer cell line OVCAR-5 did not even demonstrate CD44 expression." (PMID 31497537, 2019). "However, as HRA ovarian cancer cells were found to express very low levels of HAS2 and CD44, the in vitro effects of 4-MU in these cells may be via a mechanism other than HA-CD44 signaling." (PMID 31443261, 2019).
ovarian carcinoma (continued). "CD44 or CD44v6 expression has been shown to be correlated with poor overall survival (OS) in gastric cancer, but CD44 or CD44v6 expression has been found to not be correlated with OS in ovarian cancer; these findings suggest that some prognostic information regarding CD44 is still conflicting." (PMID 30788285, 2019). "CD44, as well as other CSC markers endoglin (CD105) and CD106 has been proved to be highly expressed in chemo-resistant ovarian cancer cells and in advanced-stage epithelial ovarian cancer tissues, suggesting CD44 may accelerate the progression of ovarian cancer by modulating the properties of CSCs." (PMID 31497537, 2019). "In summary, our results suggest that co-expression of two, three or all four HER-family members and CD44 overexpression are common in patients with Stages III and IV ovarian cancers and that EGFR and CD44 expression at different cut off values may be of prognostic value." (PMID 29731973, 2018). "Moreover, TRX-E-002-1 was effective against chemoresistant cancer stem cell (CD44+ MyD88+) populations in both 2D and 3D models as well as having potent cytotoxic activity against non-stem like ovarian cancer cells." (PMID 29572477, 2018). "Besides CD44+CD117+ cells, we have also demonstrated that ALDH+ cells isolated from the ovarian cancer cell line 2008 have all known CSC properties including high tumor-initiating capacity, and DDB2 silencing is able to increase the ALDH+ cell population in these cells." (PMID 29752431, 2018). "As both CD44 and MMP2 are inducer of epithelial-mesenchymal-transition (EMT),which strengthens our confidence that WFCD2 might participate in tumor metastasis and disease processes by regulating the progression of EMT in ovarian cancer cells." (PMID 28679402, 2017). "Moreover, ovarian cancer patients with positive CD44 expression exhibit a worse clinical outcome than those with negative CD44 expression." (PMID 28070170, 2017). "In this study, we first isolated CSCs from SKOV3 ovarian cancer cell line, and determined the stemness and self-renewal ability of these cells through both flow cytometry analysis for cell specific markers including CD133, CD44 and SOX2, as well as spheroid formation assay." (PMID 29213108, 2017). "Importantly, analogous treatment with scFvFITC:sFasL also markedly triggered apoptosis in 6 out of 7 primary patient-derived ovarian cancer samples when pretargeted with anti-CD44-FITC, but not with anti-CD33-FITC (4 out of 5)." (PMID 29038485, 2017). "Furthermore, it has been suggested that CSC markers, such as CD44, ALDH1 and CD133, may serve as valuable prognostic indicators for ovarian cancer." (PMID 28070170, 2017). "However, the role of CD44 expression in epithelial ovarian cancer has not been clarified and the clinical significance of CD44 in ovarian cancer remains controversial." (PMID 25823654, 2015). "In order to further understand the effects of CD44 in ovarian cancer stem cells, an anti-CD44 monoclonal antibody A3D8 was employed to investigate its effects and mechanisms on the proliferation and apoptosis of sphere-forming cells in the human ovarian cancer cell line SKOV-3." (PMID 26569327, 2015). "Because the miR-200c overexpression exhibited significant effects on the colony forming and on the migratory and invasion of CD44+CD117+CSCs in vitro, we sought to determine whether the miR-200c overexpression could affect the establishment and progression of ovarian cancer in vivo nude mouse model." (PMID 23842108, 2013). "Thus irrespective of its hierarchy, the presence of CD44+ ovarian cancer cells has been correlated with processes observed during ovarian cancer recurrence, such as chemoresistance, tumor repair, and carcinomatosis." (PMID 24403249, 2013).